ZYX (zyxin)
Diseases named in the same sentence as ZYX in open-access papers (continued):
Sharing a sentence is not in itself a finding about the gene and the disease.
ulcerative colitis (2 papers, 2023 to 2024). An inflammatory bowel disease involving the mucosal surface of the large intestine and rectum. "For example, studies have shown that zyxin (ZYX) is one of the core genes in ulcerative colitis, regulating its gene expression, and is expected to become a therapeutic target for ulcerative colitis." (PMID 38712343, 2024). "Additionally, in ulcerative colitis, zyxin (ZYX), RhoB, and cathepsin D (CTSD) have been identified as core genes through single-cell RNA sequencing (scRNA-seq) analysis." (PMID 38712343, 2024). "Zyxin is also involved in immune cell infiltration in ulcerative colitis." (PMID 37667739, 2023).
acute coronary syndrome (1 paper, 2025). Signs and symptoms related to acute ischemia of the myocardium secondary to coronary artery disease. "The results of our study showed a significantly higher expression of zyxin (ZYX) in patients with acute coronary syndrome (ACS) and stable coronary artery disease (CAD) than in healthy individuals." (PMID 40806205, 2025). "Statistical analysis demonstrated a significantly higher number of ZYX gene copies in acute coronary syndrome and in stable coronary artery disease as compared to controls (H = 70.99; p < 0.001)." (PMID 40806205, 2025). "The practical implications stemming from this study suggest that increased zyxin expression may serve as a potential biomarker for early repair processes occurring in the cardiac muscle of patients with acute coronary syndrome and stable coronary artery disease." (PMID 40806205, 2025).
asthma (1 paper, 2017). "Observations in human tissue samples establish a clear increase in zyxin protein in the ASM of people who died as the result of an asthma attack." (PMID 28278518, 2017). "Together, these data suggest a biophysical role for zyxin in fatal asthma." (PMID 28278518, 2017). "Importantly, we have also found increased zyxin protein expression in the airways of patients who died of asthma." (PMID 28278518, 2017). "However, it remains unclear if zyxin actually plays a role in human asthma." (PMID 28278518, 2017). "There was significantly greater zyxin staining in the ASM of people who died from asthma than in non-asthmatics and in asthmatics who died from other causes (p< 0.05)." (PMID 28278518, 2017). "Although these data implicate zyxin in the impaired ability of a DI to relax ASM in life threatening asthma, they do not determine whether high zyxin levels are a contributing cause or an effect of fatal asthma." (PMID 28278518, 2017).
atherosclerosis (1 paper, 2024). A disease characterized by the build-up of fatty material and calcium deposition in the arterial wall resulting in partial or complete occlusion of the arterial lumen. "The nuclear translocation and gene regulation processes of zyxin may be involved in the development and progression of atherosclerosis." (PMID 38712343, 2024). "Furthermore, zyxin also plays a significant role in atherosclerosis." (PMID 38712343, 2024).
bone cancer (1 paper, 2019). A primary or metastatic malignant neoplasm affecting the bone or articular cartilage. "First, through FRAP-experiments we examined the binding dynamics of fluorescently-labelled paxillin, vinculin, VASP and zyxin at FAs in two different cell-types from two different species; U2OS cells, a human bone cancer cell line, and MDCK dog kidney cells." (PMID 31320676, 2019).
breast tumours (1 paper, 2016). "Notably, moderate and high expression of Zyxin was observed in 70.7% (118 out of 167) of breast tumours compared with 5.9% (6 out of 101) of normal breast tissues, indicating a dramatic significant positive correlation between breast tumourigenesis and Zyxin expression." (PMID 27030211, 2016).
colon adenocarcinoma (1 paper, 2024). "Zyxin knockout similarly compromised the growth of syngeneic MC38 colon adenocarcinoma (Fig. EV6E–G), where the CD11b+ myeloid cells contained a high proportion of visible phospho-Zyxin labeling, while Sting−/− mice showed a decreased proportion of CD11b+pZyxin+ cells (Fig. EV6H,I)." (PMID 39304793, 2024).
coronary artery disease (1 paper, 2025). "Finally, owing to the observational nature of the study, the results do not allow for a definitive determination of a causal relationship between ZYX expression levels and the pathogenesis of coronary artery disease." (PMID 40806205, 2025). "The present study aimed to assess the transcriptional activity of the zyxin gene in patients with varying degrees of coronary artery disease and in healthy volunteers." (PMID 40806205, 2025). "The strength of this study is its innovative nature, based on assessing the expression of the zyxin (ZYX) gene at various stages of coronary artery disease, which may contribute significantly to the understanding of the molecular mechanisms of heart muscle repair after injury." (PMID 40806205, 2025). "This study aimed to evaluate the expression levels of the zyxin (ZYX) gene in patients with ACS, stable coronary artery disease (stable CAD), and healthy controls." (PMID 40806205, 2025).
diabetic nephropathy (1 paper, 2024). "In vivo, zyxin is highly up-regulated in patients suffering from diabetic nephropathy and in hypertensive DOCA-salt treated mice." (PMID 38605154, 2024). "We have seen that not only in diabetic nephropathy, a disease which is often associated with glomerular hypertension, but also in a classical glomerular hypertension model, the DOCA-salt treated mice, we have found a massive up-regulation of zyxin expression." (PMID 38605154, 2024).
endometrial cancer (1 paper, 2021). Primary or metastatic malignant neoplasm involving the endometrium (mucous membrane that lines the endometrial cavity). "Similarly, Zyxin, LIMD1 and TRIP6 mutations are linked with endometrial cancer." (PMID 33808029, 2021).
head and neck squamous cell carcinoma (1 paper, 2012). A squamous cell carcinoma that arises from any of the following anatomic sites: lip and oral cavity, nasal cavity, paranasal sinuses, pharynx, larynx, and salivary glands. "Interestingly, a decreased expression of zyxin has been reported in laryngeal squamous cell carcinoma, while an increase of FAK expression has also been reported in the head and neck squamous cell carcinomas, supporting a possible correlation between FAK and zyxin expression levels." (PMID 23267329, 2012).
herpesvirus infection (1 paper, 2024). "There are no roles for zyxin ascribed to herpesvirus infection and several hypotheses could explain the “antiviral” phenotype observed in this study." (PMID 38953638, 2024).
Human papillomavirus infection (1 paper, 2024). "Human papillomavirus infection increases zyxin nuclear translocation, possibly through the E6 protein." (PMID 38953638, 2024).
Hyperkeratosis (1 paper, 2026). Hyperkeratosis is a histopathological term defining a thickened stratum corneum and may be present in many different skin conditions, with many possible overlaps. "Subsequently, zyxin may contribute to accelerated epidermal cell turnover, hyperkeratosis, acanthosis, and dilatation of blood vessels in the psoriatic skin." (PMID 41596291, 2026).
immuno-deficiency (1 paper, 2024). "As also evidenced in immuno-deficiency mice, Zyxin KO probably relieves TAM-mediated immune suppression, from which the CD8+ T-mediated antitumor effect was compromised." (PMID 39304793, 2024).
inflammatory skin disease (1 paper, 2026). Inflammatory skin disorders covers a broad category that includes many conditions ranging in severity, from mild itching to grave medical health complications These disorders are common in people of all ages and races. "Altered zyxin expression has also been reported in several human malignancies, supporting its involvement in pathological processes beyond inflammatory skin disease." (PMID 41596291, 2026).
Moyamoya disease (1 paper, 2024). Moyamoya disease (MMD) is a rare intracranial arteriopathy involving progressive stenosis of the cerebral vasculature located at the base of the brain causing transient ischemic attacks or strokes. "In addition, recent research has used a genetic mutation burden analysis approach to identify the ZYX gene, which encodes the zyxin protein, as a new candidate gene in the pathogenesis of Moyamoya disease." (PMID 38712343, 2024). "This suggests that zyxin may be associated with the pathogenic mechanism of Moyamoya disease." (PMID 38712343, 2024).
neuroblastoma (1 paper, 2021). Neuroblastoma (NB) is the most common solid, extracranial childhood tumor. "In summary, transcriptomic expression of the C7 gene was previously identified as a risk factor for AD, whereas ZYX was known to be degraded by Aβ peptides in the neuroblastoma cell model." (PMID 34512304, 2021).
poliovirus infection (1 paper, 2017). An disease or disorder caused by infection with Enterovirus C. "We found that siRNA for ZYX moderately reduced IFNB1 promoter activation after poliovirus infection." (PMID 28928438, 2017).
sarcoma (1 paper, 2024). A usually aggressive malignant neoplasm of the soft tissue or bone. "This phenomenon may be attributed to the repositioning of zyxin within the cytoplasm rather than at cell adhesion sites in this type of sarcoma." (PMID 38712343, 2024).
systemic sclerosis (1 paper, 2024). A chronic disorder, possibly autoimmune, marked by excessive production of collagen which results in hardening and thickening of body tissues. "Confirmation through zyxin knockout mice, nude mouse models, and human systemic sclerosis (SSc) scar tissue cultures demonstrated that zyxin inhibition significantly alleviates skin fibrosis." (PMID 38712343, 2024).
testicular tumors (1 paper, 2024). "ZYX interaction with myopodin has also been reported in testicular tumors, which also play a role in suppressor tumors due to this type of interaction." (PMID 39100715, 2024).
transitional cell carcinoma of the bladder (1 paper, 2024). "To illustrate, in the evaluation of 173 subjects with transitional cell carcinoma of the bladder, it was reported that low levels of ZYX had a significant association with tumor grade and stage." (PMID 39100715, 2024).
triple-negative breast carcinoma (1 paper, 2019). An invasive breast carcinoma which is negative for expression of estrogen receptor (ER), progesterone receptor (PR), and human epidermal growth factor receptor 2 (HER2). "Higher YAP activity due to the loss of DST could, in turn, initiate a positive feedback loop, which sustains its activity, as inhibiting YAP function in the triple-negative breast cancer cell line CAL51 upregulates DST and reduces Zyxin accumulation." (PMID 31882643, 2019).
cancer (35 papers, 2007 to 2026). A tumor composed of atypical neoplastic, often pleomorphic cells that invade other tissues. "ACTN4 failure to bind to ZYX closely associates with cancer pathogenesis, because compromised cell-substratum adhesion frequently leads to increased cancer cell motility and invasiveness." (PMID 25860875, 2015). "The hypothesis of a suppressive role of ZYX can be supported by survival analysis, which showed that higher levels of cytoplasmic ZYX in cancer cells were associated with longer OS." (PMID 35740950, 2022). "The gene encoding Zyxin maps at 7q32, a chromosomal region affected in a variety of human cancers." (PMID 19874631, 2009). "The limited prior association of SEH1L, TUBA4A, ZYX, and TCF3 with chemoresistance, combined with their consistent dysregulation across cancer types, nominates them as novel and promising biomarker candidates for predicting DOX sensitivity." (PMID 41153808, 2025). "According to the literature, ZYX has various roles in cancer pathogenesis depending on the type of organ involved, test conditions, and the presence of some proteins that ZYX interacts with them." (PMID 39100715, 2024). "Further experiments and clinical studies are needed to validate and explore the exact role and clinical significance of zyxin in cancer." (PMID 38712343, 2024). "Overall, Zyxin serves as a potential therapeutic target in various fields, including cancer, cardiovascular diseases, fibrotic disorders, inflammatory conditions, and neurological disorders." (PMID 38712343, 2024). "To summarize, multiple studies suggest that zyxin plays a crucial role in the development of cancer." (PMID 38712343, 2024). "This review aims to thoroughly investigate zyxin’s role in signal transduction and its connections to significant diseases such as cancer and cardiovascular diseases." (PMID 38712343, 2024). "Zyxin regulates cell structure, adhesion, and signaling pathways, impacting diseases like cancer, cardiovascular issues, fibrosis, and inflammation." (PMID 38712343, 2024). "Recent studies have confirmed the substantial involvement of zyxin in the development of various types of cancers." (PMID 38712343, 2024). "The decreased levels of ZYX in cancer cells were also demonstrated by studies using an in vitro model of NSCLC cell lines." (PMID 35740950, 2022). "ZYX was commonly localized in mature centripetal focal adhesions, and incompetent to recruit ZYX would make the cell-substratum adhesion unstable and higher turnover, which would contribute to increased cancer cell motility and invasiveness." (PMID 35769513, 2022). "IHC reactions also showed lower cytoplasmic ZYX expression in cancer cells compared with normal cells." (PMID 35740950, 2022). "The assays on the NSCLC model also demonstrated lower levels of ZYX in cancer cells compared with control cells." (PMID 35740950, 2022). "This is in agreement with observations that zyxin influences cell migration, adhesion and proliferation as well as its potential involvement in cancer progression." (PMID 32826880, 2020). "In this context, it is interesting to note that zyxin has also been identified as a differentially transcribed gene in several types of cancers using microarray technology." (PMID 24955835, 2014). "Additional Twist1 target genes involved in cell migration include N-cadherin, identified in cancer cells, and Zyxin, identified in ECC mesenchymal cells." (PMID 22242143, 2011). "In this context it is interesting to note that also the LASP-1 binding partner zyxin has been identified as a differentially transcribed gene in several types of cancer by microarray technology." (PMID 18419822, 2008). "Researchers have observed that in certain tissue sites, zyxin could act as an oncogene, promoting the development and progression of cancer." (PMID 38712343, 2024).
cancer (continued). "Understanding the function and regulatory mechanisms of zyxin in-depth could contribute to the development of novel therapeutic strategies for cancer treatment and offer personalized treatment approaches." (PMID 38712343, 2024). "Zyxin exhibits potential as a therapeutic target in the field of cancer." (PMID 38712343, 2024). "Zyxin holds promise in cardiovascular disease, tissue repair, cancer therapy, and neuroscience." (PMID 38712343, 2024). "We also examined zyxin expression in relation to cancer stage using the GEO and TCGA databases." (PMID 37667739, 2023). "Zyxin also plays an important role in the initiation and development of cancer." (PMID 37667739, 2023). "Numerous studies have been conducted on ZYX’s role in cancer." (PMID 37626810, 2023). "Therapeutic strategies targeting zyxin should be exploited to eradicate CSCs for cancer treatment." (PMID 37667739, 2023). "Using the TIMER database, we analyzed the expression levels of ZYX in various cancers." (PMID 37626810, 2023). "The presence of ZYX in the nucleus may be related to its involvement in the regulation of gene expression responsible for the process of cancer transformation." (PMID 35740950, 2022). "Previous studies suggested that ZYX could act as both a promoter and suppressor protein in the process of tumor transformation, depending on the type of cancer." (PMID 35740950, 2022). "According to the results, zyxin might play a central role as an upstream regulator to mediate critical cancer-related signaling pathways." (PMID 31501460, 2019). "Our study demonstrates that Zyxin-Lats2–Siah2 axis may serve as a potential therapeutic target in cancer treatment." (PMID 27030211, 2016). "Although LASP-1 sequence analysis revealed no nuclear localisation signal, the classical import pathway for the nucleus, LASP-1 binds to the well-characterised shuttle proteins and transcription factors LPP and Zyxin that are upregulated in a wide variety of human cancers." (PMID 20461080, 2010). "The loss of zyxin at the sites of focal contacts without changing cellular zyxin protein levels is not restricted to cancer cells, but was also observed in human umbilical vein endothelial cells." (PMID 17211471, 2007). "By conducting a detailed analysis of zyxin’s structural features, interactions, and functional mechanisms, we aspire to unravel its potential contributions to the pathogenesis of various conditions, including cancer, cardiovascular diseases, fibrotic disorders, and others." (PMID 38712343, 2024). "Zyxin may play a dual role as an oncogene or a tumor suppressor in cancer diseases." (PMID 38712343, 2024). "Furthermore, ZYX may regulate key cancer-related signaling pathways, such as the Hippo and the Jun signaling pathways." (PMID 37547758, 2023). "This suggests that ZYX may be responsible for the resistance of cancer cells to therapy." (PMID 35740950, 2022). "Other GDTLs we detected like CXCR1, VASP, ZYX, GPR137 and GOLPH3 were reported as known markers in many cancers." (PMID 33179221, 2021). "In parallel with the migration assay, we conducted a Matrigel invasion assay to elucidate the impact of zyxin, nesprin-1, and desmoplakin on the invasive behaviors of HCT-116 cancer cells." (PMID 31501460, 2019). "Using the Pattern Comparison function in the CellMiner database, we noted that cancer cell line sensitivity to several statins in the compound library correlated strikingly with expression of TGF-β target genes SERPINE1 and ZYX." (PMID 30899443, 2019). "We used the YAP1/ABHD11‐AS1/STAU2/ZYX/p‐YAP1 signaling pathway as the entry point to explore the specific mechanisms involved in conduction of mechanical signals from the ECM in ICC cells and their impact on progression of cancer." (PMID 39703167, 2025). "The YAP1/ABHD11‐AS1/STAU2/ZYX/p‐YAP1 pathway is a useful entry point for exploration of specific mechanisms of mechanical signal conduction from the ECM in ICC cells and their impact on cancer progression." (PMID 39703167, 2025).
cancer (continued). "Next, we used the YAP1/ABHD11‐AS1/STAU2/ZYX/p‐YAP1 signaling pathway as the entry point to explore specific mechanisms via which mechanical signals are conducted from the ECM in ICC cells and their impact on the progression of cancer." (PMID 39703167, 2025). "Thus, ZYX is aberrantly expressed in HCC and promotes cancer progression via the AKT/mTOR pathway." (PMID 37547758, 2023).